JAK2 (Janus kinase 2)
Diseases named in the same sentence as JAK2 in open-access papers (continued):
Sharing a sentence is not in itself a finding about the gene and the disease.
essential thrombocythemia (continued). "Essential thrombocythaemia (ET) is a rare myeloproliferative neoplasm characterised by elevated platelet counts, megakaryocyte hyperplasia and enlargement, and one of the following: JAK2, CALR or MPL mutations, a clonal marker, or lack of evidence for reactive thrombocytosis." (PMID 33123978, 2021). "While the BCR-ABL fusion protein is the transforming agent in CML, driver mutations in JAK2, CALR, and MPL genes are variably present and are mostly mutually exclusive in Ph−MPNs, which include essential thrombocythemia (ET), polycythemia vera (PV), and primary myelofibrosis (MF)." (PMID 31963765, 2020). "Somatic mutations of calreticulin (CALR) have been described in approximately 60–80% of JAK2 and MPL unmutated Essential Thrombocythemia and Primary Myelofibrosis patients." (PMID 31332222, 2019). "For classical Philadelphia chromosome-negative (Ph-) MPN, which comprise Essential Thrombocythemia (ET), Polycythemia Vera (PV) and Primary Myelofibrosis (PMF), the clonal nature is reflected by a gain-of-function mutation in the JAK2 gene, which was identified using a functional approach." (PMID 25894969, 2015). "The classical Philadelphia (Ph) chromosome-negative MPNs comprise polycythemia vera (PV), essential thrombocythemia (ET), and primary myelofibrosis (PMF), and are associated with the driver genes JAK2, CALR, and MPL." (PMID 35805191, 2022). "Essential thrombocythaemia (ET) is a clonal MPN characterized by excess production of platelets and mature hyperlobulated megakaryocytes, with the presence of mutations in JAK2, CALR, or MPL and the absence of BCR-ABL." (PMID 34778087, 2021). "Somatic mutations in CALR gene have been reported in 60%-88% of patients with essential thrombocythemia (ET) and primary myelofibrosis (PMF) who are negative for JAK2 and MPL mutations." (PMID 30805227, 2019). "In the first case, 153 patients with JAK2 V617F positive or JAK2 V617F negative primary MF, post–essential thrombocythemia MF, or post–PV MF were enrolled." (PMID 29455651, 2018). "Nevertheless, it remains unknown which mutations exist in approximately one-third of patients with non-mutated JAK2 or MPL essential thrombocythemia (ET) and primary myelofibrosis (PMF)." (PMID 25386351, 2014). "Looking to the future, new therapies including Janus kinase 2 (JAK2) and telomerase inhibitors are promising and may become valuable to the treatment armamentarium for those afflicted with essential thrombocythemia." (PMID 25324966, 2014). "In addition, studies have shown that in patients with essential thrombocythemia and CALR mutation, there is no benefit from using low-dose aspirin, which is in contrast to patients with a JAK2 mutation." (PMID 39759619, 2024). "A 67-year-old woman with a history of JAK2-V617F–positive MPD and essential thrombocythemia (ET) presented to dermatology clinic with a 9-month history of complete hair loss." (PMID 39286822, 2024). "In this respect, it has been revealed that mutations in the genes of this pathway, including JAK2V617F in JAK2 and MPL exon 10, lead to a myeloproliferative neoplasm labeled essential thrombocythemia (ET)." (PMID 37794439, 2023). "Cases 1, 2, and 3 were of patients with PV, essential thrombocythemia (ET), and primary myelofibrosis (PMF); NGS detected JAK2 p.H538_K539delinsQL (uncommon), CALR p.E380Rfs*51 (novel), and MPL p.W515_Q516del (novel) mutations." (PMID 37396034, 2023). "In the models of the MPN polycythemia vera (PV) and essential thrombocytosis (ET), HSP90 interacted with JAK2 and HSP90 inhibitor (PU-H71) could disrupted the stability of JAK2 protein and reduced lineage-specific myeloproliferation thus inhibited the cell growth in MPN patient samples." (PMID 34956178, 2021). "However, JAK2 V617F is also found in approximately 50% of patients with essential thrombocytosis and primary myelofibrosis, rendering its presence nonspecific as a diagnostic test." (PMID 31652037, 2019).
essential thrombocythemia (continued). "CALR mutations were described recently in Janus kinase 2 gene (JAK2)-negative or MPL-negative primary myelofibrosis (PMF) and essential thrombocythemia (ET) patients." (PMID 26377485, 2016). "Although the most well-known molecular mechanism in essential thrombocythemia (ET) is the activation of JAK2/STAT, the study of mechanisms that are independent of JAK2/STAT activation related to the disease is on the rise." (PMID 38672593, 2024). "Previous study showed that somatic mutations in CRT gene were identified in Janus kinase 2 gene (JAK2 V617F)-negative or MPL-negative primary myelofibrosis (PMF) and essential thrombocythemia (ET) patients." (PMID 33591948, 2021).
leukemia (162 papers, 2008 to 2026). A malignant (clonal) hematologic disorder, involving hematopoietic stem cells and characterized by the presence of primitive or atypical myeloid or lymphoid cells in the bone marrow and the blood. "By inhibiting JAK2, the resistance mechanisms driven by altered signaling pathways are counteracted, making the leukemia cells more susceptible to conventional therapies." (PMID 40486651, 2025). "In pediatric leukemia, JAK2 mutations or dysregulation of the JAK-STAT pathway are frequently implicated in the survival and proliferation of leukemic cells, even in the presence of chemotherapy." (PMID 40486651, 2025). "Any mutations that lead to the dysregulation of JAK2 can have profound effects on these processes, contributing to the development of malignancies, including leukemia." (PMID 40486651, 2025). "In many leukemia cases, mutations in JAK2 lead to its constitutive activation, allowing leukemia cells to proliferate uncontrollably." (PMID 40486651, 2025). "Dysregulation of the JAK-STAT pathway is a key driver in the pathogenesis of leukemia, and understanding the intricate molecular mechanisms behind JAK2 mutations and their downstream effects is crucial for the development of effective therapies." (PMID 40486651, 2025). "When JAK2 mutations or aberrant STAT activation occur in leukemia cells, they often lead to the upregulation of pro-inflammatory cytokines such as IL-6, IL-10, TNF-α, and GM-CSF." (PMID 40486651, 2025). "Advances in genetic sequencing and biomarker identification can help identify which specific JAK2 mutations or dysregulated pathways are present in a particular patient’s leukemia." (PMID 40486651, 2025). "As a result, these mutations contribute to leukemia progression and chemoresistance, highlighting the importance of JAK2 in the pathogenesis of pediatric leukemia." (PMID 40486651, 2025). "These mutations often result in dysregulated JAK2 signaling that contributes to leukemia cell survival and proliferation." (PMID 40486651, 2025). "Establish international leukemia registries to collect data on JAK2 mutations, treatment responses, and outcomes." (PMID 40486651, 2025). "The exception was the assessment of the effect of Jak2-R1063H on leukemia progression, in which we demonstrated both, cell-intrinsic as well as cell-extrinsic effect of the mutation on leukemia progression." (PMID 40841769, 2025). "The JAK2 p.L884P was annotated as a somatic variant in a patient with B-ALL leukemia positive to CRLF2 rearrangement." (PMID 41009670, 2025). "The aim of this review is to provide a comprehensive analysis of the role of JAK2 in the pathogenesis of pediatric leukemia, exploring the underlying molecular mechanisms, the impact of JAK2 mutations, and the dysregulation of the JAK-STAT signaling pathway." (PMID 40486651, 2025). "The presence of JAK2 mutations in pediatric leukemia is not only a marker of disease progression but also a potential therapeutic target." (PMID 40486651, 2025). "Implement routine JAK2 mutation screening in pediatric leukemia, particularly in high-risk subtypes like Ph-like ALL." (PMID 40486651, 2025). "While its primary use has been in adult populations, its potential in pediatric leukemia, particularly those with JAK2 mutations, is being explored in clinical trials." (PMID 40486651, 2025). "Although ruxolitinib has not been widely tested in pediatric leukemia, preclinical studies and early-phase clinical trials suggest that it holds promise as a treatment for pediatric leukemias with JAK2 mutations or JAK-STAT pathway dysregulation." (PMID 40486651, 2025). "Given the genetic and molecular heterogeneity of pediatric leukemia, treatment strategies should be personalized based on the specific JAK2 mutations and JAK-STAT pathway dysregulation present in each patient." (PMID 40486651, 2025).
leukemia (continued). "The identification of JAK2 mutations in pediatric leukemia patients has led to the exploration of targeted therapies that can directly inhibit JAK2 activity." (PMID 40486651, 2025). "In pediatric leukemia, the presence of JAK2 mutations, particularly the V617F mutation, is associated with a variety of outcomes, including increased leukemia cell proliferation and resistance to apoptosis." (PMID 40486651, 2025). "Such work should not only lead to advances in cancer therapy, but also provide clues as to why some cells harboring mutations, such as JAK2, fail to drive aberrant clonal hematopoiesis, whereas others lead to MPNs, progressive disease, and lethal leukemia." (PMID 40076747, 2025). "In pediatric leukemia, JAK2 mutations can lead to the constitutive activation of the JAK-STAT signaling pathway, a process that bypasses the normal regulation by cytokine receptors." (PMID 40486651, 2025). "A national cohort study involving 302 individuals across 17 hospitals linked the JAK2 V617F mutation with an increased risk of thrombosis and a higher likelihood of progression to MF and leukemia in ET patients." (PMID 39395952, 2024). "While JAK2 V617F and exon 12 mutations are well known to contribute to development of leukemia, other variants are still considered if identified." (PMID 38572163, 2024). "The DNA‐binding function and kinase activity of Pax5‐Jak2 both contributed to leukemia development, as evidenced by mutation of the paired domain of Pax5 or the catalytic center of Jak2." (PMID 35156727, 2022). "Both fusion partners, RUNX1 and JAK2, are prominent leukemia-associated genes that are often affected by genomic rearrangements or mutations." (PMID 34299194, 2021). "Chromosomal translocations resulting in fusions deregulating JAK2 activity are implicated in leukemias as well." (PMID 31870101, 2019). "Of note, patients with concurrent JAK2 and IDH1/2 mutations have shorter leukemia-free survival, suggesting that comutations in JAK2 and in IDH1/2 can promote MPN progression and transformation." (PMID 29355841, 2018). "Taken together, these data imply that 1) the expansion properties of JAK2 mutated leukemic cells vary, 2) other subclones (e.g. KRASG12D) can grow out at the expense of the major JAK2 mutated clone, 3) JAK2 mutations can get lost while leukemia progresses." (PMID 29163799, 2017). "Strikingly, two mice injected with JAK2R683T mutated leukemic cells developed JAK2 wildtype leukemia." (PMID 29163799, 2017). "Long-range effects of mutations on domain-disorder content are partially observed also for the V617F SNP of the JAK2 kinase, a mutation mostly observed in leukaemias." (PMID 26322316, 2015). "Competitive transplantation studies showed that loss of JAK2 enabled leukemia initiating cells to outcompete the normal HSC." (PMID 25333255, 2014). "Similar results were obtained in HEL leukemia cells that harbor a JAK2-V617F mutation and the resulting hyper-phosphorylated STAT3 on Tyr-705." (PMID 24930769, 2014). "In addition to the JAK2 V617F mutation, other genetic alterations affecting JAK2 has been identified in pediatric leukemia, including deletions, amplifications, and other point mutations." (PMID 40486651, 2025). "However, mutations in the JAK2 gene can lead to its constitutive activation, bypassing the need for cytokine signaling and contributing to the unchecked growth and survival of leukemia cells." (PMID 40486651, 2025). "For example, JAK2 mutations in leukemia cells can lead to the production of cytokines and growth factors such as IL-6, IL-10, and GM-CSF, which not only stimulate leukemia cell proliferation but also recruit immunosuppressive cells, like regulatory T-cells (Tregs), to the tumor microenvironment." (PMID 40486651, 2025). "Additionally, JAK2 mutations can alter the hematopoietic microenvironment, making it more supportive of leukemia cell growth." (PMID 40486651, 2025).
leukemia (continued). "This immune escape is a significant challenge in the treatment of leukemia, and JAK2 mutations may help leukemia cells avoid the cytotoxic effects of chemotherapy and immunotherapy." (PMID 40486651, 2025). "Consequently, understanding the role of JAK2 mutations in immune regulation is critical for developing new therapeutic approaches that target both the leukemia cells and the immune evasion mechanisms they employ." (PMID 40486651, 2025). "Utilizing patient samples and in vivo modeling, we establish that leukemia-initiating clones driven by TET2 mutations can emerge independently of JAK2-mutant cells and undergo positive selection in the pro-inflammatory MPN environment, leading to parallel disease evolution." (PMID 41333431, 2025). "For example, mutations in JAK2 may contribute to immune evasion by promoting the expression of immune checkpoint molecules like PD-L1, which inhibit T-cell activation and allow leukemia cells to escape immune surveillance." (PMID 40486651, 2025). "This combination could also help in overcoming drug resistance by reprogramming the epigenetic landscape of leukemia cells, making them more susceptible to JAK2 inhibition and other therapeutic agents." (PMID 40486651, 2025). "Moreover, the Pax5::Jak2 mouse model generates a more aggressive leukemia through loss of the Pax5 WT allele caused by uniparental disomy of the Pax5::Jak2 allele, but the PAX5 WT allele is normally retained in human PAX5::JAK2 leukemia." (PMID 36387144, 2022). "PMF patients with concurrent JAK2 and IDH1-IDH2 mutations have shorter leukemia-free survival, thus suggesting that co-mutations in JAK2 and IDH1-IDH2 could cooperate to promote MPN progression and transformation." (PMID 32859092, 2020). "This is consistent with the finding that JAK2 V617F, albeit at low allelic burden, has been detected commonly in aged, healthy individuals, along with clonal hematopoiesis, and has been considered as one of the pre-leukemia-associated mutations." (PMID 32272770, 2020). "CHIP is driven by somatic mutations in leukaemia driver genes, such as Janus Kinase 2 (JAK2), Tet methylcytosine dioxygenase 2 (TET2), ASXL Transcriptional Regulator 1 (ASXL1) and DNA (cytosine-5)-methyltransferase 3A (DNMT3A), leading to reduced diversity of the blood pool." (PMID 32526214, 2020). "P190 BCR-ABL1 can mediate the tyrosine phosphorylation of STAT members, and JAK1 and JAK2 have been found to be constitutively activated by mutations in the kinase and pseudokinase domains, which explains the sensitivity of Ph+ leukaemia cells to JAK2 inhibitors." (PMID 28819864, 2018). "It is known that STAT5 phosphorylation at Tyr694 is associated, mainly, to the activation of JAK2, although other kinases could exert the same activity, as the case of the leukemia-related BCR-ABL tyrosine kinase." (PMID 25781955, 2015). "Furthermore, the combination of JAK2 inhibitors and chemotherapy could reduce the chemoresistance-associated side effects, such as myelosuppression and cytopenias, by targeting the leukemia cells more specifically." (PMID 40486651, 2025). "Additionally, combining JAK2 inhibitors with epigenetic modifiers (e.g., histone deacetylase inhibitors (HDAC inhibitors) or DNA methyltransferase inhibitors) can reprogram the leukemia cell epigenome, making them more susceptible to both JAK2 inhibition and chemotherapeutic agents." (PMID 40486651, 2025). "Acquisition of TET2 mutations is an early clonal event in MPN with mutations in Janus kinase 2 (JAK2) and myeloproliferative leukemia oncogene (MPL), implying that loss of 5-hmC levels may have a functional role in the onset and/or progression of hematological malignancies." (PMID 24202321, 2013). "In particular, JAK2 fusion partners have been identified alongside PCM1 — including BCR and ETV6— in both B- and T-lineage leukemias, further complicating diagnostic classification and therapeutic decision-making." (PMID 41530508, 2026).